TLR4 (toll like receptor 4)
Diseases named in the same sentence as TLR4 in open-access papers (continued):
Sharing a sentence is not in itself a finding about the gene and the disease.
liver disease (continued). "TLR4, a recognition receptor of LPS, is involved in the pathogenesis and progression of several liver diseases, including alcoholic and non-alcoholic steatohepatitis, fibrogenesis, and inflammatory diseases of the liver." (PMID 29057809, 2017). "Ang II initially acts in the liver to up-regulate TLR4 expression in HSCs and constrict small blood vessels, which may result in portal hypertension." (PMID 24155898, 2013). "As sCD14 complexes with LPS to activate the TLR-4 pathway, the increase in sCD14 levels that occurs with the progression of liver disease might explain the reduction in endotoxin levels, as more is bound to sCD14 and inaccessible for endotoxin detection." (PMID 20353583, 2010). "Although TLR4 SNPs, such as rs4986790, have shown protective effects in other conditions, such as viral infections, emerging evidence suggests that these mechanisms may also impact the course of liver disease in MASLD." (PMID 40332363, 2025). "Furthermore, it was found that COSM reduced LPS translocation due to intestinal flora, improved the expression of intestinal barrier function-related proteins, and ultimately reduced the expression level of the liver LPS/TLR4/NF-κB signaling pathway, thereby improving liver disease in NAFLD mice." (PMID 35736186, 2022). "The exposure to endotoxins activates macrophages via Toll-like receptor 4 (TLR4), leading to a greater production of proinflammatory cytokines and chemokines including tumor necrosis factor-alpha, interleukin (IL)-6, and IL-8, which play key roles in the progression of liver diseases." (PMID 34203178, 2021). "S. mussotii appears to be effective for treating liver diseases, such as jaundice, and we propose that S. mussotii can be used to treat NAFLD rats under conditions of hyperlipidaemia by regulating the TLR4/MyD88/NF-κB pathway." (PMID 36205548, 2022). "TLR4, a cytomembrane TLR, acts as an indispensable role in the pathological progression of inflammatory liver diseases." (PMID 29250126, 2017). "This is not surprising because TLR4, the target of pir-hsa-216911, is known to play a crucial role in developing steatosis in liver disease by mediating inflammation and metabolic abnormalities." (PMID 39824843, 2025). "By contrast, control CD133-/CD49f- cells expression levels for KRT19, CD133, NANOG, SOX2, OCT4, and TLR4 were independent of IVIG (immune serum from people with HBV+ or HCV+ liver disease) or HBIG incubation." (PMID 37744383, 2023). "However, the TLR4/MyD88-dependent and TLR4/TRIF-dependent pathways play significant roles in the escalation of inflammation in liver disease." (PMID 37446388, 2023). "All these results demonstrated that L-NAT could attenuate HIRI by regulating TLR4/NLRP3 signal, which would provide experimental data for the application of L-NAT in the field of liver diseases." (PMID 34434653, 2021). "In addition to TLR4 and MCP-1, leptin has also been known to play an active role in the progression of liver diseases." (PMID 26484872, 2015). "Therefore, the TLR4-dependent mechanism synergizes liver disease by HCV and alcohol and is partly dependent on Nanog, a TLR4 downstream gene." (PMID 21331379, 2010). "The increased TLR1/2, TLR2/6, and TLR4 expression may lead to exaggerated immune responses triggered by bacterial infection in HBV-related ACLF patients, and thus promotes the deterioration of liver disease." (PMID 29218046, 2017).
Hepatitis (74 papers, 2011 to 2026). Inflammation of the liver. "We found that fermented milk was associated with reduced activation of TLR4/NF-κB pathways, alleviating alcohol-induced liver inflammation." (PMID 41976554, 2026). "Limited studies have indicated that combined deficiency of SLAMF8 and SLAMF9 prevents endotoxin-induced liver inflammation by downregulating TLR4 expression on macrophages, and SLAMF8 can negatively regulate ROS production by macrophages." (PMID 35432371, 2022). "TFC improved intestinal epithelial permeability and reduced serum LPS levels, which in turn inhibited the TLR4-mediated NF-κB pathway that can lead to liver inflammation and attenuated the inflammatory response caused by alcohol consumption." (PMID 36712682, 2022). "To summarize, our study demonstrated new associations between SNPs in IL1B, IL12B, IL28B, TLR4 genes and symptoms of cCMV infection such as prematurity, splenomegaly, thrombocytopenia and hepatitis respectively." (PMID 32421725, 2020). "Additional studies are needed to confirm the relation of TLR4 polymorphism with increased risk of hepatitis among cCMV-infected infants." (PMID 32421725, 2020). "In the present study, we showed that ATF3 deficiency aggravated IR-induced liver inflammation by activating of mTOR/p70S6K signaling and increasing TLR4-driven inflammatory responses." (PMID 30185770, 2018). "Finally, we found that TLR4 rs4986791 polymorphism was related to hepatitis in newborn infants with cCMV infection, but the pathomechanism of this finding is unclear." (PMID 32421725, 2020). "Mice fed a high-fat diet showed an increased production of inflammatory cytokines in the Kupffer cells and increased hepatitis, but these effects were suppressed in TLR4-knockout mice, and blood ALT levels were reduced." (PMID 40077628, 2025). "The results showed that MPs and Cd induced intestinal damage and liver inflammation in broilers by interfering with the TLR4/MyD88/NF-κB pathway and intestinal flora homeostasis." (PMID 40278565, 2025). "In a model of ischemic-reperfusion liver injury, it was stated that induction of Nrf2 attenuated TLR-4-induced liver inflammation and ameliorated oxidative stress." (PMID 39917614, 2025). "The combined activation of SLAMF9 and SLAMF8 induces macrophage activity, while their downregulation modulates the expression of TLR4, thereby attenuating endotoxin-induced liver inflammation." (PMID 40473938, 2025). "Quercetin can also decrease the inflammatory mediators (e.g., high mobility group box-1) by inhibiting the axis of NF-κB/toll like receptor 4 (TLR-4), which can alleviate liver inflammation." (PMID 37810929, 2023). "The TLR4 agonist monophosphoryl lipid A is a component of Fendrix (hepatitis B vaccine) and Cervarix (human papilloma virus vaccine) (which are formulated in ASO4 adjuvant), as well as Shingrix (herpes zoster vaccine) (formulated in AS01 adjuvant)." (PMID 33439897, 2021). "In the development of NAFLD, the endotoxin‐TLR4‐NF‐κB pathway is considered as the critical factor to link intestinal microbiota dysbiosis and liver inflammation." (PMID 33400402, 2021). "MPLA, a toll-like receptor 4 (TLR4) agonist with a favorable safety profile, is already licensed as adjuvant with immunomodulatory characteristics for vaccines (Fendrix®, hepatitis B); Cervarix®, human papilloma virus)." (PMID 33808396, 2021). "Quercetin was shown to reduce the expression of high mobility group box 1 (HMGB1) and the mRNA and protein levels of TLR2 and TLR4 in liver tissues of mice with hepatitis." (PMID 31714944, 2019). "Remarkably, recent studies showed promotion of HCC by the intestinal microbiota and TLR4 and that gut-derived LPS promotes T-cell-mediated hepatitis in mice through TLR4." (PMID 30034633, 2018). "We also observed increased positive staining of alpha chemokine CXCL10, a well-known marker of chronic liver inflammation in HIV/HCV co-infection that shows a TLR4-mediated pro-apoptotic effect on hepatocytes." (PMID 29361613, 2018).
Hepatitis (continued). "In fact, Sa15–21 induces antiapoptotic genes via TLR4/MD-2 with agonistic effect and protects mice from lethal hepatitis." (PMID 29988708, 2018). "When intestinal permeability is increased, endotoxin flows into the liver from the portal vein and stimulates the endotoxin receptor on Kupffer cells, TLR4, which plays a central role in liver inflammation." (PMID 29983886, 2018). "To further understand the mechanism by which Baicalin exerts its anti-inflammatory property, we investigated the effects of Baicalin on the local activities of TLR4 and NF-κB signaling pathway in LPS-induced liver inflammation." (PMID 28868036, 2017). "Pretreatment with EA significantly decreased the expression levels of the toll-like receptor 4 (TLR4) and TLR2 implicated in hepatitis possibly by inflammation." (PMID 26442119, 2015). "Wheatly Antony (University of Otago, Dunedin, New Zealand) provided new insights into concanavalin A (ConA)-induced hepatitis and the relative roles of gut microflora, intestinal permeability, and Toll-like receptor 4 (TLR4)." (PMID 22166123, 2011). "Moreover, the mRNA and protein levels of TLR4 were increased in liver samples from patients with hepatitis and cirrhosis." (PMID 37020586, 2023). "LPS is a specific component of the Gram-negative bacteria cell wall that can cause liver inflammation in chicken, mice and piglets with activated toll-like receptor 4 (TLR4), transmitting NF-κB into nucleus that can change the abundance of inflammatory genes." (PMID 36299632, 2022). "Nevertheless, ours is the first report that links SNPs of TLR4 and hepatitis in cCMV infection." (PMID 32421725, 2020). "In the present work, the antinflammatory capability of Baishouwu extract mainly resulted in decreased levels of MyD88, TRAF6, NF-κB, IL-6 and TNF-α via the reduction of TLR4 expression in hepatitis, cirrhosis, and hepatocarcinoma stages of the HCC models induced by DEN." (PMID 31068809, 2019). "Liver inflammation was also not caused by lipopolysaccharide (LPS) contamination of the serum, because SLE-serum induced similar liver inflammation in mice with or without TLR-4 deficiency." (PMID 29988500, 2018). "MPL is a TLR4 agonist, safely used in other vaccines, such as hepatitis." (PMID 30675152, 2018). "IR-induced liver inflammation leads to the release of endogenous damage-associated molecular pattern (DAMP) molecules, which activate the TLR4 signaling cascade on Kupffer cells and the release of pro-inflammatory cytokines leading to the activation of T cells." (PMID 30185770, 2018). "LPS-mediated TLR4 activation is thought to play an essential role in MCD-feeding induced hepatitis." (PMID 30042374, 2018). "Impairment of gut microbiota homeostasis in ALD induces proliferation of gram negative pathogenic bacteria, which generate lipopolysaccharide (LPS) and translocate to liver tissue as a trigger for hepatitis by binding to TLR-4 (Toll-like receptor-4) on macrophages and neutrophils." (PMID 28228158, 2017). "We know that PA (16:0), stearic acid (18:0), OA (18:1) and LA (18:2) are capable of stimulating TLR4 signaling to produce an inflammatory response, which may eventually contribute to acute severe hepatitis." (PMID 29296119, 2017). "The reduced expression levels of TLR2, TLR4 and TLR9 mRNAs or proteins can enhance protection against T cell-mediated hepatitis in mice, and the reduced expressions of TLR4, MyD88 and NF-κB may mediate the protective effects against LPS through reducing the level of pro-inflammatory cytokines." (PMID 30909396, 2019). "Oppositely, it was found that FGP and SGP intervention significantly inhibited the expression levels of TLR4, MyD88, p‐P65/P65, p‐IκBα/IκBα, and p‐NF‐κB/NF‐κB, suggesting that FGP and SGP attenuated CTX‐induced liver inflammation." (PMID 41256228, 2025). "In HBV-induced hepatitis, the expressions of MAPK1, PTGS1, PTGS2, PLA2G4A, and TLR4 increased significantly." (PMID 37741847, 2023).
Hepatitis (continued). "Increasing levels of LPS activate Toll-like receptor 4 signaling pathways, produce proinflammatory cytokines, such as IL-17, TNF-α, IL-6, and IL-1β, and promote liver inflammation." (PMID 38138294, 2023). "Similar to our results, EA was proved to possess a protective effect on concanavalin A-induced hepatitis in mice via decreasing the expressions of TLR2 and TLR4, and suppressing NF-κB signaling pathway." (PMID 35436978, 2022). "A recent study found that the TLR4-dependent pathway in macrophages mediates the generation of IL-17-producing γδT cells and subsequent inflammation in an APAP-induced liver inflammation model." (PMID 27855209, 2016). "For example, it has been reported that the TLR4/NF-κB/MyD88 signaling pathway can induce the transcription and expression of a variety of pro-inflammatory chemokines, such as IFN-γ and TNF-α, related to liver inflammation." (PMID 38931473, 2024). "Unlike the higher expression of TLR4 in hepatitis and cirrhosis, the expression of TLR4 in liver samples of patients with hepatocarcinoma does not change." (PMID 37020586, 2023). "The results indicated that L. plantarum J26 could protect the liver by inhibiting the TLR4-mediated MAPK pathway, reducing the secretion of inflammatory factors and neutrophil infiltration, and alleviating alcohol-induced liver inflammation in mice." (PMID 36615846, 2022). "LPS causes endotoxaemia through translocation and interacts with TLR4 in the liver, and the activation of the LPS-TLR4 signalling pathway promotes the release of proinflammatory factors (e.g., TNF-α and IL-6) and exacerbates alcohol-induced liver inflammation." (PMID 36008929, 2022). "TLR4 agonist containing adjuvants have been approved as part of several vaccines: Cervarix against cervical cancer, Shingrix against shingles and Fendrix against Hepatitis B. Similarly, a TLR9 agonist is included in another Hepatitis B vaccine, Heplisav-B." (PMID 33499143, 2021). "MPLA is derived from Salmonella enterica serovar Minnesota R595 lipopolysaccharide, activates cellular immunity through the Toll-like receptor 4 (TLR4) signaling pathway, is approved for human use in Europe, and is a component of vaccines for hepatitis B and papillomaviruses." (PMID 32345645, 2020). "Overall, the results of this study indicate that ConA-induced hepatitis is marked by increased intestinal permeability and requires the presence of a functional TLR4 and of Gram-negative bacteria or their products (LPS) in the gut." (PMID 22166123, 2011). "WSF treatment effectively protects against lipid metabolism disorders and liver inflammation injury in HSHF diet-induced NAFLD mice, and its molecular mechanism might be via suppressing the TLR4/NF-κB/COX-2 inflammatory pathway to reduce the release of inflammatory cytokines in the liver." (PMID 39730994, 2024). "For example, TLR4, mRNA is overexpressed in the liver of patients with NASH compared to patients with NAFL, and TLR4 deficiency in ob/ob mice protects the liver from damage and hepatitis, but not from steatosis." (PMID 36768637, 2023). "An interesting recent study reported that inhibition of HMGB1/TLR4 intracellular signaling decreased production of NF-κB, TNF-α, and IL-6 in cholestatic liver inflammation, which further confirms the close interactions among HMGB1, TLR4, and NF-κB in the promotion of liver inflammation." (PMID 35335612, 2022). "Furthermore, TLR4 overexpression induced by DEN was decreased by Baishouwu extract, leading to the markedly down-regulated levels of MyD88, TRAF6, NF-κB p65, TGF-β1 and α-SMA in hepatitis, cirrhosis, and hepatocarcinoma." (PMID 31068809, 2019). "LPS could activate toll-like receptor 4 (TLR4) in hepatocytes and kupffer cells, and then induce the phosphorylation of nuclear factor-κB (NF-κB) and the secretions of the pro-inflammatory cytokines such as IL-6, TNF-α, and IL-1β, thereby exacerbate liver inflammation injury." (PMID 31581526, 2019).
pulmonary fibrosis (71 papers, 2009 to 2026). Chronic progressive interstitial lung disorder characterized by the replacement of the lung tissue by connective tissue, leading to progressive dyspnea, respiratory failure, or right heart failure. "In a mouse model of SSc, CD19 deficiency has been shown to significantly attenuate lung fibrosis and autoantibody production in response to TLR4 activation." (PMID 41293166, 2025). "Recently, the intersecting AOPs (AOP 347), including two MIEs, namely peroxisome proliferator-activated receptor-gamma (PPAR-γ) and toll-like receptor 4 (TLR4), associated with pulmonary fibrosis was proposed." (PMID 33809804, 2021). "Along the same line is the small heat shock protein alphaB-crystallin (HSPB5), implicated in the TLR4-dependent induction and progression of pulmonary fibrosis." (PMID 34258628, 2021). "TLR4 may further interact with inflammatory cytokines to cause pulmonary fibrosis, which is a potential pathogenesis of AAV." (PMID 38022571, 2023). "Furthermore, TLR4 expression is known to be elevated in lung biopsies of patients with pulmonary fibrosis caused by chronic inflammatory diseases." (PMID 34367191, 2021). "TLR4 deficiency ameliorates BLM-induced PF in mice, suggesting TLR4 activation is closely related to the pathogenesis of pulmonary fibrosis." (PMID 40181990, 2025). "Toll-like receptor 4 (TLR4) is a transmembrane receptor promoting pro-inflammatory signalling, that is associated with the pathogenesis of pulmonary fibrosis." (PMID 40074958, 2025). "In our study, TP-TR alleviated airway inflammation and pulmonary fibrosis in COPD rats by reducing the expression of TLR4 and TGF-β." (PMID 40845001, 2025). "Studies indicate that DHL attenuates pulmonary fibrosis in a bleomycin-induced mouse model by reducing TLR4 expression and inhibiting JNK and p38 MAPK signaling pathways." (PMID 40423444, 2025). "The decrease in autophagy induced by TLR4 was accompanied by a reduction in the degree of pulmonary fibrosis." (PMID 40238115, 2025). "The effect of TLR4 in pulmonary fibrosis via fibroblast activation has been recently emphasized, as well as its inhibition leading to an obvious fibrotic decrease." (PMID 38540252, 2024). "Rapamycin also inhibits pulmonary fibrosis induced by Toll-like receptor 4 (TLR4) antibodies or bleomycin in mice." (PMID 39544928, 2024). "The hESC-MSC-IMRC-CM can significantly inhibit BLM-induced pulmonary fibrosis in mice by inhibiting the production of ROS and proinflammatory cytokines by regulating Nox4/Nrf2 and Tlr4/MyD88 signaling pathway, respectively." (PMID 36830999, 2023). "In a recent in vivo study citrullinated vimentin was also shown to mediate development and progression of lung fibrosis through TLR4-dependent NF-κB activation." (PMID 38155185, 2023). "In lung fibroblasts, eCIRP amplifies pro-inflammatory cytokines in a TLR4-dependent manner, triggering pulmonary fibrosis." (PMID 36865547, 2023). "Inflammation is an initial driver of PF, and toll-like receptor 4 (TLR4)/MyD88-mediated inflammation and inflammatory cytokines have shown a profibrotic effect in the development of pulmonary fibrosis." (PMID 36830999, 2023). "S100A4 is also associated with TLR4 leading to elevated α-SMA expression and increased collagen I synthesis during pulmonary fibrosis." (PMID 36110858, 2022). "Fibroblast-specific deficiency of TLR4 is protective against fibrosis; however, mice deficient in TLR4, TLR2, and TLR9 exhibited aggravated pulmonary fibrosis." (PMID 36110858, 2022). "Some researchers have discovered that the TLR4/NF-κB signaling pathway can promote autophagy in the pathological phase of idiopathic pulmonary fibrosis, demonstrating that TLR4/NF-κB is required for autophagy." (PMID 36437825, 2022). "HMGB1 released after lung injury induces apoptosis resistance of fibroblasts via activation of TLR4, leading to persistent pulmonary fibrosis." (PMID 35111363, 2022).